CSPG4 (chondroitin sulfate proteoglycan 4)
Diseases named in the same sentence as CSPG4 in open-access papers (continued):
Sharing a sentence is not in itself a finding about the gene and the disease.
tumor (continued). "Therefore, both flow cytometric and immunofluorescence analyses of anti-CSPG4 IgE and IgG1 confirmed that the antibodies recognized and bound their expected tumour target-expressing cells specifically." (PMID 25073855, 2014). "Though it is not yet clear what the optimal combination and arrangement of additional intracellular signaling domains, such as 41BB or CD27 may be, the ability to successfully target tumor cell lines with variety CSPG4-directed CARs is promising." (PMID 25197555, 2014). "CSPG4 marks pericytes, undifferentiated precursors and tumor cells." (PMID 24932730, 2014). "The idea is that tumour cells may produce an NG2/CSPG4 form as a secretory molecule, which is detectable during the phase of mitosis segregation to be thereafter released into the tumour ECM." (PMID 24386429, 2013). "We hypothesized that exploiting the cytokine release capabilities of activated NK cells to reverse the anti-inflammatory axis combined with mAb9.2.27 targeting the NG2/CSPG4 may favor tumor destruction by editing pro-GBM immune responses." (PMID 24127551, 2013). "The typical multilaminar arrangement of the tumour VBM, that is a hallmark of the "garland vessels" phenotype, was revealed on sections immunolabelled with anti-Coll IV and with NG2/CSPG4 D2 antiserum, which also recognized fragmented PG, possibly released by cell surface proteolysis." (PMID 24386429, 2013). "We asked whether abrogation of NG2/CSPG4 function with shRNAs inhibited tumour growth in human GBM and melanoma xenografts." (PMID 21829586, 2011). "Therefore, CSPG4 is considered a prime tumor target antigen." (PMID 40700516, 2025). "Additionally, decitabine has been explored in conjunction with mRNA-electroporated CAR T-cells, which offer transient CAR expression to mitigate on-target/off-tumor toxicity, a critical concern given CSPG4’s low-level expression in normal tissues like the small intestine." (PMID 41029427, 2025). "However, CSPG4‐targeting therapies may trigger on‐target/off‐tumor effects due to its high expression in melanocytic nevi." (PMID 40700516, 2025). "Importantly, we show that CSPG4-targeting CAR-Ms control tumor growth in vivo." (PMID 40082557, 2025). "While further investigations are underway to better understand the role of CSPG4 in OSA and to evaluate the efficacy of its immune-targeting in combinatorial approaches with the standard of care (personal communication), focusing on a single molecular target carries the risk of tumor escape." (PMID 41375047, 2025). "Additionally, prior studies also report that CSPG4 may foster proliferation, migration, and invasion of tumor cells by regulating EMT-related pathways." (PMID 38694917, 2024). "Thus, CSPG4 might participate in cancer relapse and resistance and maintain the tumor microenvironment (TME)." (PMID 37457288, 2023). "It is important to keep in mind that low levels of CSPG4 were also found in non-malignant tissue, which might cause severe side effects due to on-target/off-tumor toxicity." (PMID 37901209, 2023). "High expression of both the EC marker KDR/VEGFR2 and the PVC marker CSPG4 showed significant association with poor overall survival (p < 0.05), suggesting that high levels of MCAM gene expression reflect greater vascularisation of tumours and associated poor prognosis." (PMID 37138793, 2023). "Interestingly, vCAFs shared many marker genes with pericytes, including platelet-derived growth factor receptor beta (PDGFRβ), Chondroitin Sulfate Proteoglycan 4 (CSPG4), and regulator of G protein signaling 5 (RGS5), which further supported its association with vascularization and tumor invasion." (PMID 38313431, 2023).
tumor (continued). "Similarly, other studies demonstrated that targeting of neuron glial antigen 2 or chondroitin sulfate proteoglycan 4 (NG2/CSPG4) with the monoclonal antibody mAb9.2.27 could inhibit tumor growth and prolong survival in GBM-bearing mouse and rat models." (PMID 36305981, 2022). "CSPG4 might mediate tumor invasion and PDL1 overexpression through EMT-related pathway." (PMID 35280756, 2022). "While these results do not discount the use of CSPG4 as a diagnostic marker, they do paint a more complex and nuanced picture of its potential application; where tumour cell CSPG4 expression is dependent on stage, as well as the changing tumour microenvironment." (PMID 36428658, 2022). "In this study, we have identified a few commonly mutated genes in pre-NACT tumor samples from either sensitive (DNAH5, CYP2D6, NUTM1) or resistant (CSPG4, TUBA3D, SLC35G5) cases, which suggest that these genes could have a potential utility for prediction of the response to NACT." (PMID 35501919, 2022). "Moreover, CSPG4 is expressed on GBM stem cells and on tumor-associated vasculature." (PMID 31779130, 2019). "Moreover, 4 somatically mutated genes, including CSPG4, DNAH11, INADL and TMPRSS13, might be promising predictive factors of PD-L1-positive expression in RCC tumor cells." (PMID 30349421, 2018). "Moreover, our study revealed that 4 somatically mutated genes, including CSPG4, DNAH11, INADL and TMPRSS13, might act as promising predictive factors of PD-L1-positive expression in RCC tumor cells." (PMID 30349421, 2018). "Moreover, since CSPG4 orchestrates multiple intracellular signaling pathways, its targeting could concurrently impair different oncogenic features of tumor cells." (PMID 28668095, 2017). "Early strategies targeting CSPG4 utilized the development of anti-idiotypic antibodies (anti-id), which target the binding sites of other anti-CSPG4 antibodies, essentially mimicking the tumor antigen’s binding site on the antibody, and thus aiming to serve as immunogens or vaccines." (PMID 29375561, 2017). "Moreover, the recognition of CSPG4 expression in other aggressive and incurable tumor histotypes may promote the spread of anti-CSPG4 vaccination strategy for the treatment of the wider population of CSPG4-positive tumor affected dogs." (PMID 28668095, 2017). "By means of its ability to act as co-receptor, binding to and presenting growth factors to their cognate RTK, CSPG4 could potentiate the activation of the mitogen-activated protein kinases (MAPK) pathway, resulting in the selective growth and survival advantage of CSPG4-positive tumor cells." (PMID 28668095, 2017). "Thus, normal pancreata should shelter scarce CSPG4-expressing pluripotent precursors or an obscure differentiated epithelial lineage, both distinct from the adult ductal cells and giving rise to certain neoplasms." (PMID 24932730, 2014). "Thus, propagation of CSPG4-expressing pericytes and tumor cells might suffice to raise systemic levels of sCSPG4 in patients with malignancies." (PMID 24932730, 2014). "As the presence of the chondroitin sulfate chain affects the cell surface distribution of CSPG4 and various functions of the glycoprotein, it has been suggested that regulation of chondroitin sulfate chain attachment may be a way tumor cells control CSPG4 activities." (PMID 24069584, 2013). "Incomplete shutdown of NG2/CSPG4 mRNA translation in the total tumour mass by the lentivirally delivered shRNA constructs, inappropriate timing of the treatment with respect to tumour growth kinetics may have contributed to the lack of survival advantage after treatment." (PMID 21829586, 2011). "However, because of the role of CSPG4 in signaling and tumor phenotype, we speculate that its interaction with P-selectin may lead to an exclusive tumor cell activation and consequently survival in circulation." (PMID 21658254, 2011).
tumor (continued). "CSPG4 exclusively presents CS-GAGs, and the data described here suggest that these structures interact with P-selectin and, therefore, may contribute to distant metastasis of tumor cells." (PMID 21658254, 2011). "Here, we validate chondroitin sulfate proteoglycan 4 (CSPG4) as a highly expressed, prognostic antigen in HPV‐negative HNSCC that drives tumor proliferation." (PMID 41698053, 2026). "Considering the findings of our study, on‐target/off‐tumor reactions emanating from cellular therapies, such as CAR‐T cells specific for CSPG4, on melanocytic nevi can be expected." (PMID 40700516, 2025). "In TNBC models, bispecific or dual-target CAR-T designs, such as those targeting B7-H3/CSPG4 or mesothelin/NKG2D ligands, have demonstrated potent cytotoxicity and superior tumor regression compared with single-target CAR-T approaches." (PMID 41348261, 2025). "Other regulators of tumor biology, including PTPRS, CSPG4, SPRED1, CD59, and PROCR, were all downregulated upon CBX3 knockdown." (PMID 39545414, 2024). "The specific effects of decline in CSPG4 and CHST15 on the interactions of tumor cells with neighboring cells, inflammatory cells, and the extracellular matrix require further evaluation." (PMID 37813168, 2024). "In conclusion, this study showed that CSPG4 was expressed in EOC and related to the tumor aggressiveness, including proliferation, invasion, and sphere formation." (PMID 38338902, 2024). "Previous studies revealed that knockdown CSPG4 can reduce expression of EMT markers (E-cadherin, N-cadherin) and key EMT regulator (Snail), and then inhibit tumor migration/invasion." (PMID 38808892, 2024). "The authors suggested that the T cells expressing both receptors will selectively lyse tumour cells because of simultaneous activation with CSPG4 expressed on the tumour and CD20 expressed either on the tumour or on bystander/tumour-infiltrating B cells." (PMID 39409881, 2024). "In another study, second-generation CSPG4-redirected CAR-Ts using murine-based scFvs reported target antigen-dependent cytotoxicity and cytokine secretion against several tumor (including BC) cell lines." (PMID 36900394, 2023). "In recent years, researchers have attributed a number of roles to CSPG4, which might further validate its importance as a target antigen; such roles include contribution to the formation of metastatic lesions, contribution to tumor aggressiveness, and arranging tumor progression signals." (PMID 38146364, 2023). "In this study, we also demonstrate that depleting PBMCs of monocytes impaired CSPG4 IgE-mediated ADCC and tumor growth restriction in vivo." (PMID 37185332, 2023). "In line with the in vitro findings, CSPG4 CAR T cells led to outgrowth of tumor cells, while tumor clearance was only observed in the group with CCR-expressing CSPG4-CAR T cells." (PMID 37901209, 2023). "Aiming to prevent off-tumor toxicity while maintaining a high cytolytic potential, we combined a chimeric co-stimulatory receptor (CCR) and a CSPG4-directed second-generation chimeric antigen receptor (CAR) with moderate potency." (PMID 37901209, 2023). "The antimelanoma activity of CSPG4-CAR.CIK was successfully confirmed in vivo, obtaining a significant tumor growth inhibition of an HLA-defective Mel xenograft in immunodeficient mice." (PMID 37993874, 2023). "For this reason, our approach was focused on combining a low-affinity CSPG4-targeting CAR, which by itself only showed weak anti-tumor cytotoxicity, with an anti-CD20 chimeric co-stimulatory co-receptor (CCR)." (PMID 37901209, 2023). "CSPG4 has been suggested as a biomarker for GBM that facilitates tumorigenesis and tumor progression." (PMID 35202840, 2022).
tumor (continued). "Here, we analyzed CSPG4 expression in 309 GIST samples and searched for correlations with both the clinicopathological features including clinical outcome and the tumor immune landscape." (PMID 35267618, 2022). "Chondroitin sulfate proteoglycan 4 (CSPG4) is a cell surface proteoglycan and its release from pericytes and vascular smooth muscle cells is very important in tumor angiogenesis." (PMID 36422502, 2022). "The use of CSPG4-CAR-T cells is primarily intended for metastasized patients, which generally bear a heavy tumor burden with extensive spread to the body." (PMID 36291817, 2022). "Of the 16 metabolism-related genes, we found AOC2, IDUA, GPC2, CSPG4, TPST1, and CYP1B1 to be differentially expressed between tumor and normal tissues at the protein level." (PMID 35281080, 2022). "Of the 16 metabolism-related genes, we found that AOC2, IDUA, GPC2, CSPG4, TPST1, and CYP1B1 were differentially expressed between tumor and normal tissue at the protein level according to the Human Protein Atlas (HPA) cohort." (PMID 35281080, 2022). "In the three remaining mice of this group, tumor growth resumed after 50 days following treatment (tumor size at end of study +/- SEM per group in mm3: PBS 836 ± 31, anti-CSPG4-(PDD) 155 ± 85, isotype-(PDD) 834 ± 38)." (PMID 32331483, 2020). "In this treatment setting, the anti-CSPG4-(PDD) administered in two 2 mg/kg doses significantly restricted tumor growth compared with isotype-(PDD) ADC, PDD payload alone, anti-CSPG4 plus unconjugated PDD or buffer control-treated groups." (PMID 32331483, 2020). "Based on their MFIs, GD2, HER2, B7H3, CSPG4, L1CAM (CD171), and Lewis Y were chosen as tumor targets for further in vitro screening." (PMID 33303017, 2020). "Another important observation was that the amount of tumor-specific EVs (enriched using tumor-specific markers anti-EGFR, anti-MAGEA3, anti-EpCAM, and anti-CSPG-4) varied among different patients." (PMID 33158181, 2020). "In our opinion, they remain visible for a long time in the proliferative tumor due to their GFAP positivity and NG2/CSPG4 expression, undergoing the pathoplastic influence from tumor cells, mainly in relation to vessels." (PMID 32599896, 2020). "In aggregate, CSPG4-CAR-T cells have the potential to mount a concerted attack against various targets, including primary TNBC cells, stromal cells, and tumor surrounding blood vessels." (PMID 31779130, 2019). "Altogether, these results show that TETARs specifically kill tumor cells expressing either one of the targeted antigens or both through the equipment with a gp100-specific TCR and a CSPG4-specific CAR." (PMID 31137488, 2019). "Deletion of Ng2/Cspg4 in established tumors (KrasFRT-STOP-FRT-G12D/+; p53FRT/FRT; Rosa26Cre-ER-T2/+; Ng2/Cspg4f/f) resulted in a significant reduction in tumor size when compared with the KrasFRT-STOP-FRT-G12D/+; p53FRT/FRT; Rosa26+/+; Ng2/Cspg4f/f tumors." (PMID 29196603, 2018). "In this feasibility study, several proteins were identified that positively correlated to tumor tissue content including IF6, ARF4, MUC18, UBC12, CSPG4, PCNA, PMEL and MAGD2." (PMID 28445515, 2017). "Using MRM‐based quantification, it was found that VCAM1, CALB1, CSPG4, and VTDB also dynamically changed with tumor progression." (PMID 28980450, 2017). "However, since in several malignancies tumor cells have been reported to escape T-cell recognition, more and more researchers have focused their attentions on mAb-based therapies and several studies have investigated the potentiality of mAb-based anti-tumor strategies directed against CSPG4." (PMID 28668095, 2017). "The study did not report a significant correlation between the T cell responses against a HLA-DR presented CSPG4 peptide, quantified through IFN-γ production, and the tumor burden of patients." (PMID 29375561, 2017).
tumor (continued). "Therefore, anti-CSPG4 vaccination strategy could have a substantial impact for the treatment of the wider population of spontaneous CSPG4-positive tumor affected dogs with a priceless translational value and a revolutionary implication for human oncological patients." (PMID 28668095, 2017). "In an increasing number of tumours, prognostic implications of NG2/CSPG4 are being unveiled and these discoveries accentuate the potential of the PG as a therapeutic target." (PMID 25935541, 2015). "After 168 hours the percentage of CSPG4 positive tumor cells killed by the CD4+ and CD8+ cell fraction rose up to 97%, as only 3% viable tumor cells were left." (PMID 26469402, 2015). "Application of the Cox proportional hazard model revealed that T3-T4 classification of the tumour (HR, 6.36, p = 0.001) and de novo expression of NG2/CSPG4 mRNA (HR, 6.76, p = 0.017) were independent, robust prognostic factors for local tumour recurrence." (PMID 25935541, 2015). "Free CS-4 chains or CS-4 chains on CSPG4 bound to proMMP-2 and MT3-MMP forming a complex that facilitated the activation of proMMP2 by MT3-MMP-expressing tumor cells to enhance invasion and metastasis." (PMID 24205138, 2013). "CSPG4 and CHST11 expression showed an increase in tumor tissue over normal tissue in 10 out of 14 sample pairs and 8 out of 15 sample pairs, respectively." (PMID 21658254, 2011). "Additionally, bispecific or single-domain antibody fragments against tumor antigens (e.g., GD2, CSPG4) are being explored for radiolabeling with 177Lu or 89Zr to deliver targeted radiotherapy." (PMID 41008677, 2025). "The hypoxia–HIF1α axis may further reinforce this program, as HIF1α induces xCT in OSA cells, enhances CSPG4 expression, and upregulates TLR2 in tumor and immune cells." (PMID 41375047, 2025). "While few studies have investigated CSPG4 in BLCA, it is potentially upregulated in tumor tissues." (PMID 40918470, 2025). "Their ability to upregulate antigens such as CSPG4 and NKG2DL addresses the critical challenge of low antigen density in solid tumors, while their compatibility with combinational strategies offers hope for overcoming tumor heterogeneity." (PMID 41029427, 2025). "It is possible that a decline in abundance of CSPG4 and CHST15 by treatment with exogenous ARSB may improve recognition of the tumor cells by infiltrating immune cells or may enhance contact inhibition." (PMID 37813168, 2024). "Notably, these markers have previously been linked to different cell types, including endothelial cells (CD44, ENG, F3, MCAM, and ITGB1), immune cells (CD14, CD44, CSPG4, ENG, HLA-DR/DP/DQ), and neuronal cells (NCAM1), as well as astrocytes and tumor cells." (PMID 39594703, 2024). "There is a significant difference in CSPG4 expression between tumor (T) versus non-tumor (NT) (p < 0.0001) breast tissues, with varying differences in CSPG4 expression between patient tumor tissue sections." (PMID 37432459, 2023). "Although expression levels are clearly lower than in tumor cells, CSPG4 is also found on non-malignant tissue, such as pericytes and small intestine." (PMID 37901209, 2023). "A similar result was obtained with normal donor PBMC-derived CSPG4 CAR T cells following repetitive co-culture with stressed vs. non-stressed tumor cells." (PMID 37714830, 2023). "Then, strong and sustained cytotoxicity on a panel of different target cancer cells and increased release levels of IFN-γ and TNF-α were found in normal donor PBMC-derived B7-H3 CAR T cells or CSPG4 CAR T cells, respectively, following repetitive co-culture with stressed tumor cells." (PMID 37714830, 2023). "Various glycosaminoglycans (hyaluronic acid, heparin) and proteoglycans (CD44, CSPG4, MUC-1) have been suggested as potential cancer targets due to their important roles in tumor pathogenesis and their upregulation in malignant tissues but are also expressed in healthy tissues." (PMID 37118819, 2023).